RAB22A (RAB22A, member RAS oncogene family)
Description:
The small GTPases Rab are key regulators of intracellular membrane trafficking, from the formation of transport vesicles to their fusion with membranes. Rabs cycle between an inactive GDP-bound form and an active GTP-bound form that is able to recruit to membranes different sets of downstream effectors directly responsible for vesicle formation, movement, tethering and fusion. RAB22A plays a role in endocytosis and intracellular protein transport. Mediates trafficking of transferrin/TF from early endosomes to recycling endosomes. Required for NGF-mediated endocytosis of NTRK1, and subsequent neurite outgrowth. Has low GTPase activity.
Tractability: Antibody: its Gene Ontology location is reachable by antibodies, with high confidence; UniProt places it where antibodies can reach, with medium confidence. PROTAC: ubiquitination databases record sites on it; its protein half-life has been measured.
Target class: Enzyme; Hydrolase
Gene: Protein-coding gene on chromosome 20 (58,309,706 to 58,367,507, forward strand). Ensembl gene ENSG00000124209.
Subcellular location: Endosome membrane; Cell membrane; Early endosome; Late endosome; Cell projection, ruffle; Cytoplasmic vesicle; Cytoplasmic vesicle, phagosome; Cytoplasmic vesicle, phagosome membrane
Subcellular location (Human Protein Atlas): Golgi apparatus; Vesicles
Pathways (Reactome):
Metabolism of proteins: RAB geranylgeranylation
Gene Ontology:
Molecular function: G protein activity; GDP binding; GTP binding; GTPase activity; protein binding
Biological process: endocytosis; endosome organization; regulation of vesicle size
Cellular component: cytoplasmic vesicle; early endosome; extracellular exosome; phagocytic vesicle; plasma membrane; endosome membrane; late endosome; phagocytic vesicle membrane; ruffle
Genetic constraint (gnomAD): Loss-of-function variants: 10 observed, 20.12 expected, observed/expected ratio (o/e) 0.5, 90% interval 0.31 to 0.84. The upper end of that interval is the gene's LOEUF score, 0.84, which puts it in group 3 of 6, group 1 being the genes least tolerant of losing a copy. Missense variants: 141 observed, 194.84 expected, observed/expected ratio (o/e) 0.72, 90% interval 0.63 to 0.83. Synonymous variants: 73 observed, 70.32 expected, observed/expected ratio (o/e) 1.04, 90% interval 0.86 to 1.26.
Homologues: Orthologues: chimpanzee RAB22A (99% identical), guinea pig RAB22A (99% identical), dog RAB22A (98% identical), mouse Rab22a (97% identical), rat Rab22a (96% identical), macaque RAB22A (95% identical), rabbit RAB22A (92% identical), tropical clawed frog rab22a (89% identical), zebrafish rab22a (88% identical), pig RAB22A (83% identical). Paralogues in human: RAB31 (71% identical), RAB5A (46% identical), RAB5C (45% identical), RAB5B (44% identical), RAB21 (43% identical), RAB2B (42% identical), RAB11B (42% identical), RAB11A (41% identical), RAB18 (41% identical), RAB4B (41% identical), RAB4A (40% identical), RAB14 (40% identical), and 56 more.
Diseases named in the same sentence as RAB22A in open-access papers:
RAB22A is named in the same sentence as 47 diseases in open-access papers, as found by Europe PMC text mining. Sharing a sentence is not in itself a finding about the gene and the disease. The quoted sentences say what the papers report.
breast carcinoma (31 papers, 2015 to 2025). "Intriguingly, RAB22A has been implicated in facilitating breast cancer metastasis in orthotopic mouse models." (PMID 40493409, 2025). "While RAB22A has been confirmed to be associated with breast cancer metastasis, few studies have investigated ITIH3 and CDV3." (PMID 40500539, 2025). "Elevated RAB22A mRNA levels in primary breast cancers were associated with significantly decreased overall survival and distant metastasis-free survival." (PMID 27486767, 2016). "Hypoxic breast cancer-derived MVs caused increases in tumor metastasis and invasion, which were dependent on the expression of RAB22A within the MVs." (PMID 26601108, 2015). "Rab22A overexpression is detected in primary breast tumours and associated with decreased overall and metastasis‐free survival whereas Rab22A knockdown impairs breast cancer metastasis in an orthotopic mouse model." (PMID 34401050, 2021). "Besides, Rab22A deficiency inhibits metastasis in an orthotopic mouse model of breast cancer." (PMID 38695990, 2024). "asiatica and compare their cytotoxic potential against breast cancer cell line MCF7 by studying their impact on the Rab22A gene along with apoptotic pathway genes and proteins." (PMID 39213285, 2024). "RAB22A is highly expressed in colorectal cancer, hepatocellular carcinoma and breast cancer, and participates in extracellular vesicle secretion, EMT and immune regulation." (PMID 38431306, 2024). "Under hypoxic conditions, Rab22a mediates MV shedding in breast cancer cells, thus promoting breast cancer metastasis." (PMID 39085827, 2024). "In one study, RAB22A mediated the migration and invasion of breast cancer cells by promoting exosome secretion, which can be regulated by targeting RAB22A through tumor suppressor gene miR-19b." (PMID 38431306, 2024). "In breast cancer patients, overexpression of Rab22A in the primary tumor is correlated with reduced overall and metastasis-free survival." (PMID 38695990, 2024). "asiatica and Z. arabicum and evaluating their therapeutic potential against breast cancer, targeting the Rab22A gene and its protein." (PMID 39213285, 2024). "RAB22A acts as a prognostic marker in breast cancer and inhibits invasion and metastasis of breast cancer cells through secretion of exosomes." (PMID 32759795, 2020). "A second study on breast cancer cells came to a similar conclusion, and found that cells exposed to hypoxia overexpressed the small GTPase RAB22A in a HIF dependent manner, leading to increased formation of EVs in breast cancer." (PMID 30783517, 2019). "HIFs and RAB22A mediate the formation of larger EVs and MVs, and stimulate breast cancer invasion and metastasis." (PMID 29534557, 2018). "Exposure of human breast cancer cells to hypoxia augments MV shedding mediated by the HIF-dependent expression of the small GTPase Rab22A, which co-localizes with budding MVs at the cell surface." (PMID 29534557, 2018). "RAB22A gene expression was reported to be significantly increased in breast cancers compared with normal breast tissue." (PMID 27486767, 2016). "Mir-193b decreases in breast cancer cells, which allows the expression of its target genes DNAJC13 and RAB22A, and promotes breast cancer progression." (PMID 26347258, 2015). "RAB22A was reported as an oncogenic gene in breast cancer, CRC, osteosarcoma, and ccRCC." (PMID 38850457, 2025). "Investigation of the role of hypoxia-inducible factors (HIFs) in breast cancer invasion and metastasis revealed that hypoxia in breast cancer cells induces an increase in the expression of the Ras-related protein Rab-22A (RAB22A) which colocalizes with increased expression of ectosomes formation." (PMID 39773634, 2025). "For example, Rab22a has been reported to mediate EXs secretion of breast cancer cell and could promote cell proliferation and migration." (PMID 35770324, 2022). "miR-193b could regulate the proliferation, invasion and migration of breast cancer cells through RAB22A." (PMID 34707990, 2021).
breast carcinoma (continued). "Exposure of breast cancer cells to hypoxia enhances microvesicle (MV) shedding, which is regulated by HIF-dependent expression of Rab22A." (PMID 38695990, 2024). "RAB22A is a member of RAS oncogene family, and its expression is increased in many cancers such as breast cancer, colorectal cancer, osteosarcoma and liver cancer, and it is involved in the proliferation, migration and immune regulation of malignant tumors." (PMID 38431306, 2024). "In hypoxic breast cancer cells, increased release of MPs requires HIF-α dependent expression of the small GTPase RAB22A, which is a protein that localizes to budding MPs52." (PMID 31676796, 2019). "Hypoxic conditions are known to increase MV and exosome release from a variety of breast cancer cell lines, including MCF-7, MDA-MB-231, and SK-BR3, which requires hypoxia-inducible factor- (HIF-) dependent RAB22A expression." (PMID 26601108, 2015). "In breast cancer, elevated MCF2L-AS1 expression predicts shortened patient survival, while in colorectal cancer, it drives tumor progression by sponging miR-105–5p to promote RAB22A-mediated metastasis." (PMID 40644833, 2025). "Finally, only 1 (BCAS4/BCAS3), 1 (BSG/NFIX), 2 (STX16/RAE1, RAB22A/MYO9B) and 0 fusions have been reported by all the tools within the considered breast cancer cell lines." (PMID 28114882, 2017). "Moreover, it has been demonstrated that the role of hypoxia-induced exosomes in stimulating breast cancer invasion and lung metastasis is by a mechanism involving RAB22A expression, since hypoxia mediated ECM invasion and lung colonization is lost after RAB22A knockdown." (PMID 32764376, 2020).
osteosarcoma (25 papers, 2017 to 2025). A usually aggressive malignant bone-forming mesenchymal neoplasm, predominantly affecting adolescents and young adults. "The E3 ligase STIP1 homology and U-box-containing protein 1 (STUB1) catalyzes the K63-linked ubiquitination of K112 of the Rab22a-NeoF1 fusion protein, which promotes the lung metastasis of osteosarcoma." (PMID 39048965, 2024). "The AB22A-NeoF1 fusion gene encodes the Rab22a-NeoF1 fusion protein, which coordinates various mechanisms to facilitate lung metastasis in osteosarcoma." (PMID 39048965, 2024). "In contrast to the RabL31–36 protein that arises by truncation, the abnormal Rab22a proteins that occur in osteosarcoma are fusion proteins consisting of the first 1–38 amino acids of Rab22a followed by various sequences encoded by different regions of chromosome 20." (PMID 34222337, 2021). "For example, SNHG3 upregulates Ras-related protein 22a (Rab22a) by sponging miR-151a-3p, thereby promoting migration and invasion in osteosarcoma." (PMID 39349640, 2024). "The research focused on evaluating the expression levels of SNHG3, miRNA-151a-3p, and RAB22A, alongside assessing the invasive and migratory potentials of osteosarcoma cells." (PMID 39349640, 2024). "Rab22a‐NeoF fusion protein has recently been reported as a promising target for osteosarcoma lung metastasis." (PMID 36529692, 2023). "In a mouse experiment, EVs were found to carry the Rab22a-NeoF1 fusion protein to promote osteosarcoma cell metastasis to the lung via PYK2 activation of RhoA in donor cells in osteosarcoma." (PMID 38037077, 2023). "Our findings illustrate that the lysosomal degradation of Rab22a‐NeoF1 fusion protein is targetable for drug treatment of osteosarcoma lung metastasis, such as with Sorafenib and Regorafenib." (PMID 36529692, 2023). "Consistently, by upregulating PINK1, Sorafenib and Regorafenib can inhibit osteosarcoma lung metastasis induced by Rab22a‐NeoF1." (PMID 36529692, 2023). "Collectively, both Sorafenib and Regorafenib inhibited lung metastasis of osteosarcoma by inducing PINK1 to target the lysosomal degradation of Rab22a‐NeoF1 fusion protein." (PMID 36529692, 2023). "It has been reported that SNHG3 promotes the overexpression of Rab22a by regulating miRNA-151A3p in osteosarcoma, thereby promoting the invasion and migration potentials of osteosarcoma cells." (PMID 35757470, 2022). "The Kang laboratory generated a cell-penetrating synthetic peptide corresponding to the first 1–10 amino acids in Rab22a, based on their discovery that fusion proteins containing Rab22a1–38 bind SmgGDS-607 in osteosarcoma." (PMID 34222337, 2021). "Here, we report that osteosarcoma Rab22a-NeoF1 fusion protein, together with its binding partner PYK2, is sorted into exosomes by HSP90 via its KFERQ-like motif (RVLFLN142)." (PMID 33568623, 2021). "These proteins consist of the N-terminal portions of RabL3 or Rab22a, and exhibit enhanced binding to SmgGDS-607 and SmgGDS-558 in pancreatic cancer and osteosarcoma, respectively, and are also detected in breast cancer." (PMID 34222337, 2021). "Different targets of miR-203a have been defined in the context of other cancers, like RAB22A (encoding Ras-related protein Rab-22A) and BIRC5 (encoding survivin) in osteosarcoma." (PMID 32760222, 2020). "Then, through coimmunoprecipitation and other techniques, Rab22a-NeoF1 was uncovered to promote osteosarcoma lung metastasis by activating RhoA." (PMID 32839478, 2020). "For instance, SNHG3 sponges miR-151a-3p as a ceRNA to upregulate Ras-related protein 22a (Rab22a) expression, thus increasing cell migration and invasion of osteosarcoma cells." (PMID 33292213, 2020). "A previous study demonstrated that the SNHG3/miRNA-151a-3p/Rab22a axis regulates invasion and migration of osteosarcoma." (PMID 33292213, 2020).
osteosarcoma (continued). "In this study, we provide evidence that C646 antagonizes the enhancement of migration, invasion and lung metastasis induced by Rab22a-NeoF1 in osteosarcoma cells and in the orthotopic osteosarcoma metastasis model in vivo." (PMID 32685017, 2020). "Two targeted drugs, Sorafenib and Regorafenib, could upregulate PINK1 to diminish osteosarcoma lung metastasis induced by Rab22a‐NeoF1." (PMID 36529692, 2023). "More importantly, by two screenings of the kinase library and kinase inhibitors library, we discovered that Sorafenib and Regorafenib as multi‐kinase inhibitors diminished osteosarcoma lung metastasis induced by Rab22a‐NeoF1 fusion protein via the PINK1/Rab22a‐NeoF1 axis." (PMID 36529692, 2023). "Further studies have shown that PYK2 was enriched in osteosarcoma derived exosomes by binding to the RAB22A-NeoF1 fusion protein, thereby inducing RhoA activation in RAB22A-NeoF1-negative receptor osteosarcoma cells to promote their migration, invasion, and lung metastasis." (PMID 34712664, 2021). "Consequently, lung metastases of its recipient osteosarcoma cells are promoted by this exosomal Rab22a-NeoF1 fusion protein, and this event can be targeted by disrupting its interaction with PYK2 using a designed internalizing RGD peptide." (PMID 33568623, 2021). "Since Rab22a-NeoF1 only occurs in a subset of cancer cells, we sought to mimic the heterogeneous osteosarcoma tumors in mice by orthotopically injecting U2OS/MTX300-luc cells alone or together with either ZOS-M-shNC or ZOS-M-shRAB22A-NeoF1 at both the 10:1 and 10:2 ratios." (PMID 33568623, 2021). "SNHG3 forms an SNHG3/miRNA‐151a‐3p/RAB22A pathway to regulate the cell migration in osteosarcoma." (PMID 32248648, 2020). "And when using specific targeting peptides of Rab22a, the interaction between Rab22a-NeoF1 and SmgGDS-607 was abolished, which inhibited lung metastasis and increased the survival time, suggesting a potential therapeutic target for osteosarcoma lung metastasis." (PMID 32839478, 2020). "Rab22a-NeoF1 is acetylated at K7; such an acetylation facilitates its interaction with SmgGDS607 and leads to the excessive activation of RhoA GTPase to be transferred on membrane, which in turn promotes metastasis in osteosarcoma." (PMID 32685017, 2020). "The K7R mutant of Rab22a-NeoF1 lacks its binding to SmgGDS607 and subsequently lost its promoting functions, such as activation of RhoA, cell migration, invasion and lung metastasis in osteosarcoma in vitro and in vivo, which are also diminished by p300/CBP inhibitor C646." (PMID 32685017, 2020). "g., C646) may be efficient to prevent osteosarcoma lung metastasis induced by Rab22a-NeoF1." (PMID 32685017, 2020). "To investigate whether the K7 acetylation of Rab22a-NeoF1 regulates its promoting osteosarcoma metastasis, we generated their stable U2OS cell lines and U2OS/MTX300 cell lines (U2OS/MTX300 cell line is a methotrexate-resistant derivative of the U2OS human osteosarcoma cell line)." (PMID 32685017, 2020). "Furthermore, using the orthotopic osteosarcoma metastasis model in vivo and the tail vein injection metastasis model in vivo, the lung metastases of 143B-Luc cells were significantly increased in mice pre-educated by Rab22a-NeoF1-CM compared to those pre-educated by Vector-CM." (PMID 33568623, 2021). "Furthermore, via either knockdown or overexpression of Rab22a-NeoF1 in osteosarcoma cell lines and tumor tissues, they verified that Rab22a-NeoF1 could promote tumor migration and invasion, which might be a potential therapeutic target in patients with metastatic osteosarcoma." (PMID 32839478, 2020). "Inhibition of miR-203 stimulated osteosarcoma cell growth by targeting TBK1, proliferation and RAB22A." (PMID 29228583, 2017).
osteosarcoma (continued). "of Rab22a-NeoF1 was also responsible for the interaction of Rab22a-NeoF1 with PYK2, and the 1–10 a.a.-iRGD peptide abolished the exosomal Rab22a-NeoF1-mediated lung metastases of its negative recipient cells using the orthotopic osteosarcoma metastasis model." (PMID 33568623, 2021). "Collectively, these results demonstrate that the conditioned medium derived from tumor cells positive for RAB22A-NeoF1 promotes its negative osteosarcoma cells to metastasize to lungs." (PMID 33568623, 2021). "In osteosarcoma, SNHG3 could promote the progression of SNHG3 by absorbing miRNA-151a-3p and then upregulating RAB22A expression." (PMID 33596916, 2021). "Furthermore, miR-203 is significantly downregulated in osteosarcoma samples and cell lines compared to controls, while its target gene RAS-related protein Rab22A (RAB22A) is overexpressed." (PMID 32806571, 2020). "Furthermore, the transfer of Rab22a-NeoF1 fusion protein from osteosarcoma cells to negative tumor cells via EVs contributes to the formation of pre-metastatic niche in osteosarcoma." (PMID 35059436, 2021). "Since SA, but not C646, inhibited cell viability of osteosarcoma cells, we tried to explore whether C646 could repress the promoting functions of Rab22a-NeoF1." (PMID 32685017, 2020). "In this report, we found that the K7 of Rab22a-NeoF1, acetylated by p300/CBP while de-acetylated by both HDAC6 and SIRT1, plays a key role in its binding to SmgGDS607, and consequently affects its activation of RhoA and promotion of cell migration, invasion and lung metastasis in osteosarcoma." (PMID 32685017, 2020). "Furthermore, using the orthotopic osteosarcoma metastasis model in vivo, the enhancement of lung metastases was abolished in both 143B-Luc and U2OS/MTX300-Luc cells treated with exosomes derived from ZOS-M cells stably knockdown RAB22A-NeoF1 compared to those derived from ZOS-M control cells." (PMID 33568623, 2021). "Using the orthotopic osteosarcoma metastasis model in vivo, lung metastases of U2OS/MTX300-Luc cells stably expressing Rab22a-NeoF1, but not Rab22a-NeoF1-K7R, were dramatically enhanced compared to those stably expressing Vector." (PMID 32685017, 2020). "Most importantly, the exosomes from cells stably expressing the 141-142AA mutant of Rab22a-NeoF1 lacked the enhancement of cell migration and invasion in both U2OS and 143B cells, as well as the lung metastases of 143B-Luc cells in the orthotopic osteosarcoma metastasis model in vivo." (PMID 33568623, 2021).